RB1CC1 (RB1 inducible coiled-coil 1)
Diseases named in the same sentence as RB1CC1 in open-access papers (continued):
Sharing a sentence is not in itself a finding about the gene and the disease.
anemia (2 papers, 2019 to 2021). A reduction in the number of red blood cells, the amount of hemoglobin, and/or the volume of packed red blood cells. "Mice deficient for FIP200/RB1CC1 also displayed perinatal lethality associated with anemia and increased frequency of immature erythroid cells." (PMID 34207482, 2021).
atherosclerosis (2 papers, 2024 to 2025). A disease characterized by the build-up of fatty material and calcium deposition in the arterial wall resulting in partial or complete occlusion of the arterial lumen. "AP000892.6 interacts with the RB1CC1 RNA, which may play a role in atherosclerosis via its function in forming the autophagosome." (PMID 38334359, 2024).
colon adenocarcinoma (2 papers, 2012 to 2022). "We found a general increase of RB1CC1 in response to RSL3 and erastin in HepG2, gastric cancer MKN‐45, lung adenocarcinoma (LUAD) H1299, PC9 and A549, LUSC H226, pancreatic cancer (PACA) SW1990, HCC Bel‐7402 and colon adenocarcinoma HCT29 cells." (PMID 35220675, 2022).
diabetic kidney disease (2 papers, 2025). Progressive kidney disorder caused by vascular damage to the glomerular capillaries, in patients with diabetes mellitus. "RB1CC1 was downregulated in the urine of diabetic kidney diseased patients compared to the control group." (PMID 40533788, 2025).
glioma (2 papers, 2013 to 2015). A benign or malignant brain and spinal cord tumor that arises from glial cells (astrocytes, oligodendrocytes, ependymal cells). "Several genes down-regulated in BAT such as PRDM2, TCF7L2, RB1CC1, ATP2A2 are involved in the pathogenesis of other type of cancers, but not in gliomas." (PMID 23472076, 2013).
liver fibrosis (2 papers, 2024 to 2025). "The tissue microarray analysis suggested that RB1CC1 protein levels were also upregulated in liver fibrosis tissues compared to normal tissues, a finding that aligns with previous animal and cell experiments." (PMID 38481992, 2024). "Meanwhile, knocking down RB1CC1 was found to inhibit the activation of hepatic stellate cells and alleviate liver fibrosis." (PMID 38481992, 2024). "More importantly, knockdown of RB1CC1 in a cell model has been shown to inhibit hepatic stellate cell activation and alleviate liver fibrosis." (PMID 38481992, 2024). "This is the first study to identify RB1CC1 in HF, which may influence immune cell infiltration and aggravate liver fibrosis." (PMID 38481992, 2024). "This is the first study to identify RB1CC1 in HF, which may promote the progression of liver fibrosis by regulating macrophage, Th17 cell, natural killer cell and CD56dim natural killer cell." (PMID 38481992, 2024). "Thus, in vitro, in vivo, and tissue multi-level data support our main findings that RB1CC1 is abnormally high expressed in liver fibrosis and could potentially serve as a promising biomarker for this disease." (PMID 38481992, 2024). "Therefore, RB1CC1 may be a marker that promotes liver fibrosis." (PMID 38481992, 2024). "In the mouse liver fibrosis experiment, ATG5, RB1CC1, and PARK2 were at higher levels in HF group than those in HC group." (PMID 38481992, 2024). "Moreover, we confirmed the involvement of ATG5, PARK2, and RB1CC1 in HF in a mouse liver fibrosis model, among which RB1CC1 was never before reported in liver fibrosis." (PMID 38481992, 2024).
renal cell carcinoma (2 papers, 2022). "The overexpression of RB1CC1 decreased the phosphorylation of PyK2 and doxorubicin, which increased RB1CC1 expression and reduced the size of xenografted renal cell carcinoma tumors." (PMID 36555115, 2022). "A recent study has manifested the repression of RB1CC1 in renal cell carcinoma (RCC) cells advancement." (PMID 35068326, 2022).
Viral infection (2 papers, 2021 to 2023). "RB1CC1 has also been shown to influence viral infection, as a depletion of RB1CC1 led to an increase of encephalomyocarditis virus replication." (PMID 37901834, 2023). "RB1CC1 was up-regulated at 16 h with virus infection but was down-regulated upon NIC treatment at 16 h." (PMID 37901834, 2023).
Alzheimer disease (1 paper, 2021). A progressive, neurodegenerative disease characterized by loss of function and death of nerve cells in several areas of the brain leading to loss of cognitive function such as memory and language. "Another target, RB1CC1 is essential for autophagy induction, RB1CC1 insufficiency causes neuronal atrophy and is involved in the pathology of Alzheimer’s disease." (PMID 34539341, 2021).
Cerebellar atrophy (1 paper, 2025). Cerebellar atrophy is defined as a cerebellum with initially normal structures, in a posterior fossa with normal size, which displays enlarged fissures (interfolial spaces) in comparison to the foliae secondary to loss of tissue. "For example, the neural-specific deletion of RB1CC1 resulted in cerebellar atrophy associated with axonal degeneration and neuronal death." (PMID 40149422, 2025).
cholangitis (1 paper, 2024). An acute or chronic inflammatory process affecting the biliary tract. "Further, RB1CC1 was found to be associated with cholangitis, a disease closely associated with IBD." (PMID 38741190, 2024). "Additionally, JAK1 was associated with essential tremor (333.1, P = 1.03 × 10−2) and RB1CC1 displayed an association with cholangitis (575.1, P = 1.02 × 10−2) and IL6ST with noninfectious gastroenteritis in UK Biobank (558, P = 3.14 × 10−2)." (PMID 38741190, 2024).
colorectal tumors (1 paper, 2009). "The mRNA upregulation and relative rarity of RB1CC1 biallelic mutation observed in MSI-H colorectal tumors appears to support potential oncogenic roles of RB1CC1 in the colon." (PMID 19888451, 2009). "This screening identified frequent mutation and aberrant mRNA upregulation of RB1CC1 in MSI-H colorectal tumors, which deserves further investigation of its potential involvement in colorectal tumorigenesis." (PMID 19888451, 2009). "This study also identifies RB1CC1 as a novel target of frequent mutation and aberrant upregulation in MSI-H colorectal tumors." (PMID 19888451, 2009).
diabetes (1 paper, 2025). "Also, mTOR, nuclear factor NF-kappa-B (NFKB1) and RB1-inducible coiled-coil 1 (RB1CC1) are autophagy-related genes that affect diabetes pathogenesis." (PMID 40533788, 2025).
encephalomyelitis (1 paper, 2021). Inflammation of the brain and the spinal cord. "Additionally, animals with a dendritic cell-specific deficiency in RB1CC1/Fip200 were protected against encephalomyelitis." (PMID 34539341, 2021).
herpesvirus infection (1 paper, 2024). "Additionally, myeloid-specific knockout of several autophagy genes (RB1CC1, Beclin1, ATG3, ATG5, ATG7, ATG14, or ATG16L) in animals subjected to herpesvirus infection results in elevated inflammation and prevented viral reactivation from latency." (PMID 38447109, 2024).
Infertility (1 paper, 2022). "Although conditional knockout of RB1CC1/FIP200 in the reproductive tract of female mice has been reported to result in infertility due to implantation failure, endometrial carcinogenesis has not been evaluated." (PMID 35433698, 2022).
Insulin resistance (1 paper, 2022). Increased resistance towards insulin, that is, diminished effectiveness of insulin in reducing blood glucose levels. "The expression of autophagy related genes (ATG14, RB1CC1/FIP200, GABARAPL1, and WIPI1) and protein LC3BII and ATG5 in skeletal muscle in patients with T2DM following in severe insulin resistance are downregulated." (PMID 35252293, 2022).
lung carcinoma (1 paper, 2022). "Therefore, we examined the subcellular localisation of RB1CC1 and its association with ferroptosis sensitivity in lung cancer." (PMID 35220675, 2022). "Nuclear localisation of RB1CC1 correlated with lipid peroxidation in clinical lung cancer specimens." (PMID 35220675, 2022). "On the basis of RB1CC1 subcellular localisation, lung cancer was divided into cytoplasmic (cyto), nuclear (nucl) and joint cytoplasmic‐nuclear (cyto/nucl) subtypes." (PMID 35220675, 2022). "RB1CC1 was also upregulated in our institutional lung cancer cohort (n = 348)." (PMID 35220675, 2022). "Approximately 48.97% (95/194) LUAD and 47.4% (73/154) LUSC specimens displayed RB1CC1 nuclear subcellular localisation, suggesting a large portion of lung cancer may benefit from ferroptosis‐based therapy." (PMID 35220675, 2022). "Additionally, using ferroptosis‐resistant H460 lung cancer cells, we evaluated whether targeting the RB1CC1 pathway removes cellular resistance to ferroptosis." (PMID 35220675, 2022). "We evaluated the levels of 4‐HNE in 348 lung cancer specimens and found that the cyto‐subtype had the lowest 4‐HNE levels, while the nucl‐subtype had the highest ones, demonstrating that lipid peroxidation is possibly dependent on RB1CC1 subcellular localisation." (PMID 35220675, 2022).
renal carcinoma (1 paper, 2022). A carcinoma arising from the epithelium of the renal parenchyma or the renal pelvis. "Rb1-inducible coiled-coil 1 (RB1CC1) is a tumor suppressor that is considered to be a therapeutic target in renal carcinoma." (PMID 36555115, 2022).
triple-negative breast carcinoma (1 paper, 2010). An invasive breast carcinoma which is negative for expression of estrogen receptor (ER), progesterone receptor (PR), and human epidermal growth factor receptor 2 (HER2). "In this cohort, RB1CC1(−) status correlated significantly with PR-negative and triple-negative phenotypes, as well as chemotherapy, and these findings seem to be closely related because chemotherapy was often applied to the PR-negative and/or triple-negative breast cancer patients." (PMID 21203526, 2010).
type 2 diabetic (1 paper, 2020). "The expression of skeletal muscle autophagy-related genes (ATG14, RB1CC1/FIP200, GABARAPL1, SQSTM1/p62 and WIPI1) and proteins (LC3BII, SQSTM1/p62 and ATG5) were also significantly decreased in type 2 diabetic patients, and skeletal muscle autophagy was decreased." (PMID 32082422, 2020).
vitiligo (1 paper, 2024). Generalized well circumscribed patches of leukoderma that are generally distributed over symmetric body locations and is due to autoimmune destruction of melanocytes.
tumor (63 papers, 2009 to 2025). "Everolimus is an mTOR inhibitor, disrupt tumor proliferation under overexpression of RB1CC1, which is a recently identified tumor suppressor implicated in autophagic and apoptosis." (PMID 38443363, 2024). "The decrease in RB1CC1 expression is caused by tumor-derived lactate, which disrupts the balance between pro- and anti-apoptotic factors, enhancing tumor immune evasion." (PMID 37675121, 2023). "Our study identified RB1CC1 as a key regulator to sensitise ferroptosis in tumour cells and proposes a novel ferroptosis‐associated regulatory signalling pathway." (PMID 35220675, 2022). "RB1CC1 encodes a tumor-suppressing protein that interacts with signaling pathways to regulate cell growth, proliferation, migration, apoptosis, and autophagy." (PMID 31639064, 2019). "Our findings indicate that RB1CC1‐associated signalling sensitises tumour cells to ferroptosis and that targeting RB1CC1 may be beneficial for tumour treatment." (PMID 35220675, 2022). "Together, these results indicate that activating JNK stimulates RB1CC1 to sensitise ferroptosis and inhibits tumour growth." (PMID 35220675, 2022). "Together, these findings indicate that Rb1cc1 is critical for the efficacy of ferroptosis‐based anti‐tumour treatments." (PMID 35220675, 2022). "Nonetheless, the inhibitory effect of IKE on tumour growth was remarkably reduced in Rb1cc1+/– mice as compared with that in WT mice." (PMID 35220675, 2022). "We discovered that nuclear translocation of RB1CC1 upon induction of ferroptosis triggers transcriptional reprogramming, which is essential for increasing the sensitivity of tumour cells to ferroptosis." (PMID 35220675, 2022). "RB1CC1 is upregulated by lipid ROS and that nuclear translocation of phosphorylation of RB1CC1 at Ser537 was essential for sensitising ferroptosis in tumour cells." (PMID 35220675, 2022). "We strongly recommend that targeting RB1CC1 is a promising perspective to reinforce ferroptosis‐based therapy against tumours." (PMID 35220675, 2022). "They discovered that deletion of Rb1cc1, an autophagy-related gene, sensitizes tumor cells to T cell killing, improving immune checkpoint blockade efficacy in mouse models." (PMID 36230955, 2022). "RB1CC1 conferred a significant relative hazard (p<0.0001) in addition to the risks of chemotherapy, tumor size, lymph node status, TNM class, ER, PR, triple-negative cancer, and RB1." (PMID 21203526, 2010). "RB1CC1 mutant was predicted to lose a microRNA-accessible loop structure at a putative binding site for the tumor-suppressive microRNA, miR-138." (PMID 19888451, 2009). "Specifically, RB1CC1 has been associated with migration and invasion ability in HCC, and RB1CC1-related signaling pathways sensitized tumor cells to ferroptosis, demonstrating that targeting RB1CC1 could promote the treatment of HCC." (PMID 38481992, 2024). "It was proved that Circ-CUL2 exerted its tumor suppressive influence via miR-888-5p/RB1CC1 axis." (PMID 35068326, 2022). "We thereby speculated that the faster growth of RB1CC1 KO tumours are the combined results from increased cell proliferation and decreased autophagy." (PMID 35220675, 2022). "Other studies showed that RB1CC1 is critical for autophagy in tumour cells." (PMID 35220675, 2022). "We next evaluated the clinical and translational significance of RB1CC1 in tumours." (PMID 35220675, 2022). "Our findings have shown that RB1CC1 sensitises tumour cells to ferroptosis." (PMID 35220675, 2022).
tumor (continued). "Specifically, these mutations are located on five tumor suppressors (SDHA, RB1CC1, PTCH1, DMBT1, BCR) and eight proto-oncogenes (MERTK, CSF1R, MYB, ROS1, PCM1, FGFR2, MYH11, BRCC3) and have an allele frequency lower than 0.01 in the Genome Aggregation Database (GnomAD)." (PMID 33466296, 2021). "Moreover, knockout of RB1CC1 can make tumor cells more easily killed by T cells and improve the therapeutic effect of immune checkpoint inhibitors in mice." (PMID 34539341, 2021). "RB1CC1 is a potential regulator of the tumor suppressor, RB1." (PMID 32920960, 2020). "Knockout of the RB1CC1 gene elicited a drastic increase in tumor-infiltrating CD8+ T-cells in mice." (PMID 28753959, 2017). "Patient and tumor characteristics stratified by nuclear RB1CC1 expression." (PMID 21203526, 2010). "We next examined whether RB1CC1 is essential for IKE‐induced suppression of tumour growth." (PMID 35220675, 2022). "Nuclear expression of RB1CC1 could be important for tumor suppression." (PMID 20614030, 2010). "Tumor-suppressor genes, including APC, BARD1, HMMR (RHAMM), KLLN, LZTR1, MCPH1 (BRIT1), MLH1, NF1, RB1CC1 (FIP200), SLC22A18, and SPTBN1, have been found to increase the risk of disease and tumor development." (PMID 40941673, 2025). "Numerous tumor-related genes, such as HMGA2, RB1CC1/FIP200, SRCIN1, STAT3, and PTEN, are targeted by miR-20a." (PMID 33504017, 2021). "Several tumour suppressor genes (BAI3, PEG3, PRDM2, RB1CC1) along with the natural killer receptor KLRC1 were also down regulated in BAT." (PMID 23472076, 2013). "RB1CC1, also named as FIP200 (200kda FAK family interacting protein), is a tumor suppressant." (PMID 35068326, 2022). "A putative RB1CC1-targeting microRNA, miR-138, is a tumor-suppressor miR and downregulated in non-colonic malignancies." (PMID 19888451, 2009). "To investigate why RB1CC1 KO tumours grew faster than control cells even without IKE treatment, we compared the cell proliferation capacity of control and RB1CC1‐KO Bel‐7402 cells and found that RB1CC1 KO cells demonstrated a more accelerated cell proliferation rate than the control cells." (PMID 35220675, 2022). "Furthermore, IKE did not suppress tumour growth and induce lipid peroxidation in the RB1CC1 KO group as it did in the control group." (PMID 35220675, 2022). "Two DEGs (PIK3C2A and RB1CC1) that closely related to autophagy initiation were significantly inhibited, suggesting that ZBTB38 downregulation also blocked autophagy, an important mechanism that protects the cells from programmed cell death, thus accelerating apoptosis of tumor cells." (PMID 30697495, 2019). "Cytoplasmic RB1CC1 seems to play no role as a direct tumor suppressor." (PMID 21203526, 2010).
tumor (continued). "However, cytoplasmic RB1CC1 seems to play no role as a tumor suppressor activating the RB1 pathway." (PMID 20614030, 2010). "However, treating cells with JNK agonists Clolar and OXA neither stimulated nuclear translocation of RB1CC1 nor influenced ferroptosis sensitivity in H460 cells, suggesting that JNK agonists might only reinforce ferroptosis‐based therapy in ferroptosis‐inducible tumour cells." (PMID 35220675, 2022).